LAMP2 (lysosome associated membrane protein 2)
Diseases named in the same sentence as LAMP2 in open-access papers (continued):
Sharing a sentence is not in itself a finding about the gene and the disease.
diabetes (9 papers, 2015 to 2025). "Atg5 and LAMP2 were highly expressed in control mice, and both diabetes and I/R alone resulted in LAMP2 and Atg5 reduction." (PMID 36562207, 2023). "This apparent uncoupling of Stmn2 and glucagon suggests that Stmn2 is required for the trafficking of glucagon to Lamp2+ lysosomes in the normal regulation of glucagon secretion, and that, in diabetes, this step is impaired." (PMID 34923907, 2022). "In some cases, gene expression differed significantly between groups from early in the disease course, for example, Tbk1 from 6 weeks of age, and in other cases expression diverged later, for example, Lamp2 at 12 weeks and diabetes onset." (PMID 26366287, 2015). "Additionally, decreased expression of LAMP-2 induced by diabetes may attenuate the fusion of the mature autophagosomes with cytosolic lysosomes, eventually inhibiting autophagolysosome development." (PMID 36841820, 2023). "In detail, STZ-induced diabetes remarkably reduced the expression of ATG-1, ATG-5, Beclin-1, and LAMP-2." (PMID 36841820, 2023). "Some genes such as Sirt7, Tbk1 and Lamp2 were significantly overexpressed in the group developing diabetes after 17 weeks, but expression did not correlate with time of diabetes onset." (PMID 26366287, 2015).
melanoma (9 papers, 2013 to 2023). A malignant, usually aggressive tumor composed of atypical, neoplastic melanocytes. "In contrast, low levels of LAMP2 expression benefit immunotherapy, as patients with a low level of LAMP2 responded better to the ICB treatment than those with a high level of LAMP2 in an anti-PD1-treated melanoma cohort." (PMID 37640708, 2023). "The hierarchy of endogenous LAMP2 mRNA expression (LAMP2B > LAMP2A > LAMP2C) was consistent among two distinct human melanoma cell lines, DM331 and SLM2-Mel." (PMID 30211163, 2018). "Cellular levels of total LAMP-2, detected with an antibody recognizing all isoforms, were increased 1.5- to 4-fold in melanoma cells likely due to the increase in LAMP2C mRNA." (PMID 30211163, 2018). "Treatment of vemurafenib resistant TPF-12-293 melanoma cells with [pazopanib + AR42] promoted the co-localization of HDAC6 with LAMP2." (PMID 29137331, 2017). "Indeed, increased release of exocytosis after TRPV4 agonist stimulation was accompanied with up-regulation of LAMP2 in human melanoma A375 cells." (PMID 35456964, 2022). "To address whether differential regulation of LAMP2 isoforms is observed in human melanomas, we exposed melanoma cells to IFN-γ." (PMID 30211163, 2018). "While not previously linked to LAMP-2 stability, proteasome activity did increase in melanomas with ectopic LAMP-2C." (PMID 30211163, 2018). "We found that this process is exacerbated in the case of senescent melanoma cells, as revealed by the exposure of lysosomal membrane integral proteins LAMP1 and LAMP2 in their plasma membrane." (PMID 36087066, 2022). "Western blot analysis of melanoma cells revealed similar electrophoretic migration of ectopic LAMP-2C and other LAMP-2 isoforms on SDS-PAGE." (PMID 30211163, 2018). "Melanoma SK‐MEL‐103 cells treated with the CDK4/6 inhibitor, palbociclib, displayed SAβGal staining and increased protein levels of the lysosomal membrane proteins LAMP1 and LAMP2." (PMID 36087066, 2022). "The diffuse appearance and similar electrophoretic migration of LAMP-2C ectopically expressed with or without a myc tag in melanomas, was consistent with a high degree of glycosylation observed with other LAMP-2 isoforms." (PMID 30211163, 2018).
Alzheimer disease (7 papers, 2014 to 2024). A progressive, neurodegenerative disease characterized by loss of function and death of nerve cells in several areas of the brain leading to loss of cognitive function such as memory and language. "Using the developed method, with defined and limited variability, we report increased cerebrospinal fluid levels of three LAMP2 peptides in Alzheimer’s disease subjects (n = 14), as compared to non-Alzheimer’s disease controls (n = 14)." (PMID 26924951, 2016). "We here present a tool which can be used for exploring the relevance of the level of LAMP2 as a potential measure of lysosomal dysfunction in Alzheimer’s disease or other neurodegenerative diseases." (PMID 26924951, 2016). "It is well described that in other neurodegenerative diseases, such as Alzheimer’s disease, neurotoxic peptides induce the activation of lysosomal pathways and the increase of the lysosomal marker LAMP2 levels." (PMID 24472629, 2014). "Lamp2’s CSF concentration decreases in Parkinson’s disease (PD) and increases in Alzheimer’s disease (AD), but whether its CSF concentration changes during normal aging has not been investigated." (PMID 29867441, 2018). "Altered LAMP2 levels in cerebrospinal fluid may indicate endo-lysosomal dysfunction in Alzheimer’s disease." (PMID 26924951, 2016). "LAMP-1, LAMP-2, and LC3 levels are significantly increased in the CSF from patients with Alzheimer’s disease, and the autophagy biomarkers LC3B and Beclin1 correlate with clinical outcomes and disease severity in patients who experienced an acute stroke." (PMID 30442917, 2018).
glycogen storage disease (7 papers, 2008 to 2025). "In 2005, Arad and colleagues first described mutations in lysosome-associated membrane protein 2 encoded by LAMP2 and protein kinase gamma-2 encoded by PRKAG2 in glycogen storage disease-associated genes mimicking the clinical phenotype of HCM." (PMID 18478063, 2008). "Even if it was traditionally classified as a glycogen storage disease, it is not caused by a primary disorder of glycogen metabolism, it is caused by mutations in the LAMP2 gene, which encodes lysosome-associated membrane protein 2, essential for normal autophagy and lysosomal function." (PMID 41463072, 2025).
ovarian carcinoma (7 papers, 2022 to 2025). A malignant neoplasm originating from the surface ovarian epithelium. "In addition, a reduced expression of LAMP2 has been associated with a decreased resistance to both cisplatin in human ovarian carcinoma cells and azacitidine in acute myeloid leukemia." (PMID 38240686, 2024). "Thereby, we revealed a signature of three TOP genes encoding proteins within our dataset (CORO1B, LAMP2, MSLN), which were differentially expressed in ovarian cancer patients compared to healthy individuals." (PMID 41551606, 2025). "The results revealed that the colocalization of autophagy regulator (LC3) and lysosome (LAMP2) significantly increased in CACNA1G-AS1 knockdown ovarian cancer cells, while IGF2BP1 upregulation reversed this change." (PMID 37304234, 2023). "Our findings revealed a simultaneous presence of mitophagy and lysosome markers, indicating a clear rise in the joint presence of LC3 and LAMP2 in ovarian cancer with reduced ITGB2 levels, while PI3K/AKT up-regulation could save this pathological change." (PMID 38345576, 2024). "First, we detected the colocalization of ferritin and lysosome labels, and the results confirmed that the colocalization of ferritin (FTH1) and lysosome (LAMP2) significantly increased in CACNA1G-AS1 knockdown ovarian cancer cells, while IGF2BP1 upregulation reversed this change." (PMID 37304234, 2023). "First, we detected co-localization of ferritin and lysosome labels, and the results show that the co-localization of NCOA4 and lysosome (LAMP2) was significantly inhibited in C-MYC-over-expressed ovarian cancer cells, while NCOA4 up-regulation could reverse this change." (PMID 36552889, 2022). "Mitochondrial division inhibitor 1 (Mdivi-1), significantly inhibited mitophagy induction and suppressed the toxicity of pyrimethamine in ovarian cancer cells, as exhibited by MT-CO2/LAMP2 colocalization." (PMID 40918465, 2025).
pancreatic cancer (7 papers, 2012 to 2025). "As Gal-9 is involved in pancreatic carcinoma and Lamp2 is also associated with pancreatitis, we investigated whether Gal-9 has a function in the homeostasis of pancreatic acinar cells, which, similar to intestinal Paneth cells, are an autophagy-active secretory cell type." (PMID 32855403, 2020). "Localization of MUC1 in lysosomes was further confirmed by co-staining pancreatic cancer cells with the lysosomal marker Lamp2." (PMID 22912777, 2012). "Additionally, to confirm whether THM induced autophagy in pancreatic cancer cells, we further assessed the expression levels of multiple autophagy-related proteins, including ATG5, ATG7, LAMP2, SQSTM1 and LC3B, in THM-treated cells." (PMID 40756353, 2025).
vasculitis (7 papers, 2020 to 2026). "Serum lysosome-associated membrane protein 2 (LAMP-2) concentrations distinguish PAN from antineutrophil cytoplasmic antibodies (ANCA)-associated vasculitis at proposed cutoff values and correlate with disease activity." (PMID 41596381, 2026). "The aim of this study was to explore the association of serum anti-lysosomal-associated membrane protein-2 (anti-LAMP-2) antibody with vasculitis combined with hypertension (VAS-HTN)." (PMID 35356030, 2022). "Finally, our study did not evaluate the comparison of diagnostic performance between anti-LAMP-2 and other vasculitis diagnosis markers, such as anti-endothelial cell antibody (AECA)." (PMID 35356030, 2022). "In antineutrophil cytoplasmic antigen (ANCA)- mediated vasculitis, an aggressive autoimmune disease which frequently causes crescentic glomerulonephritis, a subset of patients were found to have autoantibodies to LAMP2, suggesting that lysosomes may play a role in the pathogenesis of this disease." (PMID 37071647, 2023). "Previous reports have demonstrated an increase in LAMP-2 protein in sera from adults with a medium-sized vessel vasculitis subtype called polyarteritis nodosa (PAN)." (PMID 38612581, 2024). "Herein, we demonstrate an increased prevalence and concentration of ANCA that are specific for LAMP-2 in children with PR3/MPO-ANCA-negative vasculitis affecting medium (MVV) and large (LVV) blood vessels." (PMID 38612581, 2024). "LAMP-2 is a component of the lysosomal membrane and is believed to partake in the pathogenesis of vasculitis by binding to neutrophils, which then infiltrate small vessels of the skin." (PMID 37374366, 2023). "Recent studies suggest that anti-LAMP-2 antibody has been involved in the pathogenesis of vasculitis." (PMID 35356030, 2022). "Therefore, whether the anti-LAMP-2 antibody is associated with vasculitis remains controversial." (PMID 35356030, 2022). "The correlation analysis showed a significant positive correlation between serum anti-LAMP-2 antibody levels and the Birmingham Vasculitis Activity Score (BVAS) and hypersensitive C-reactive protein (Hs-CRP) (all P < 0.05)." (PMID 35356030, 2022). "While LAMP-2-ANCA were detected in 88% of our cohort of pediatric vasculitis samples, the majority were deemed low titers (<1,000 ng/ml)." (PMID 33613565, 2020). "This ELISA was used to screen a cohort of pediatric patients with AAV, to assess, for the first time, if LAMP-2-ANCA are prevalent in pediatric vasculitis." (PMID 33613565, 2020). "Therefore, the role of anti-LAMP-2 antibodies in vasculitis is still far from clear." (PMID 35356030, 2022). "Although LAMP-2-ANCA titers did not significantly differ between patients with AAV versus ANCA-negative vasculitis, only AAV patients had high concentrations (>1,500 ng/ml) of LAMP-2-ANCA." (PMID 33613565, 2020). "Similar to LAMP-2-ANCA-positive control sera, LAMP-2-ANCA concentrations in pediatric vasculitis samples ranged from undetectable (n = 4 patients) to levels over 3 μg/ml (n = 3 patients)." (PMID 33613565, 2020). "LAMP-2-ANCA titers were also not correlated with elevated systemic disease activity as indicated by a validated pediatric vasculitis clinical scoring algorithm, pVAS, and general inflammatory markers, CRP and ESR." (PMID 33613565, 2020). "The prevalence of LAMP-2-ANCA has not been assessed in children with vasculitis due in large part to the rarity of the disease relative to adult-onset vasculitis." (PMID 33613565, 2020). "We next assessed whether concentrations of LAMP-2-ANCA correlated with standard clinical measures of disease activity, namely, C-reactive protein (CRP, mg/L), erythrocyte sedimentation rate (ESR, mm/hr), and pediatric vasculitis activity score (pVAS)." (PMID 33613565, 2020).
vasculitis (continued). "Likewise, LAMP-2-ANCA titers did not correlate with the pediatric vasculitis activity score (pVAS) (n = 46, p = 0.9737), a pediatric adaption of the adult BVAS, which is a cumulative weighted score of disease activity of nine organ systems (mean pVAS = 20.4 +/- 8.8 at TOD, n = 46)." (PMID 33613565, 2020).
colorectal cancer (6 papers, 2016 to 2025). A primary or metastatic malignant neoplasm that affects the colon or rectum. "According to the current state of knowledge, the increase in CMA activity, and thus the overexpression of the LAMP-2 protein, causes the progression of cancers, including colorectal cancers." (PMID 36830954, 2023). "In another study, analogous results were obtained; colorectal cancer cells were characterized by increased expression of LAMP-2." (PMID 36830954, 2023). "LAMP2 is also highly expressed in poorly differentiated human colorectal cancer, prostate cancer, hepatocellular carcinoma, adenoid cystic carcinoma, and lung adenocarcinoma and represents a novel molecular biomarker for these cancer types." (PMID 35530327, 2022). "Differential transcriptional patterns of BECN1, PINK1, and LAMP2 were observed across colorectal cancer stages, suggesting that distinct autophagy pathways may be differentially regulated in inflammation-associated and sporadic colorectal tumorigenesis." (PMID 41614861, 2025). "The aim of this study was to determine, via in silico methods, miRNA’s importance in BECN1, LAMP2, and PINK1 regulation and their possible role in the epigenetic changes in colorectal cancer." (PMID 33322704, 2020). "The study aimed to find those microRNAs (miRNAs) important in BECN1, LAMP2, and PINK1 regulation and to determine the possible role of the epigenetic changes in examined colorectal cancer using an in silico approach." (PMID 33322704, 2020). "In colorectal cancer epithelium, LAMP1 and LAMP2 levels are increased, suggesting that LAMPs are related to neoplastic progression, but there is no direct association between such up-regulated expression and cell proliferation." (PMID 27627761, 2016). "The transcriptional activity of genes involved in the autophagy process (LAMP-2, BECN1, PINK1, FOXO1) in colorectal cancer biopsies in four clinical stages of adenocarcinoma (CSI, CSII, CSIII, CSIV) was compared with that of controls (colon samples assessed as histopathologically normal)." (PMID 36830954, 2023).
ischemia (6 papers, 2015 to 2020). A hypoperfusion of the BLOOD through an organ or tissue caused by a PATHOLOGIC CONSTRICTION or obstruction of its BLOOD VESSELS, or an absence of BLOOD CIRCULATION. "Much of LC3 signals were overlapped with LAMP2 signals, and the lysosome-associated LC3 puncta were significantly increased by ischemia." (PMID 32796816, 2020). "Intriguingly, in the young hearts, Atg5 and LC3‐II levels were higher, and lysosome formation (LAMP2) was lower during ischemia and reperfusion than during the sham operation." (PMID 31944526, 2020). "The LAMP-2 protein levels were significantly lower in the I/R group than in the sham group at 24 h post-ischemia (P < 0.01)." (PMID 30046966, 2018). "Another study of ischemia-reperfusion injury found autophagosome accumulation and depletion of LAMP2." (PMID 26248051, 2015). "However, Atg5, LC3‐II, and LAMP2 levels were lower in the aged hearts than in the young hearts during ischemia and reperfusion." (PMID 31944526, 2020).
lung carcinoma (6 papers, 2011 to 2025). "Similarly, low expression of LAMP2 was associated with the malignancy of lung cancer." (PMID 37986192, 2023). "In lung cancer, miR-487b-5p downregulated LAMP2 protein, affecting their autophagy regulation and leading to drug resistance." (PMID 37986192, 2023). "In temozolomide-resistant lung cancer cells, LAMP2 expression was downregulated by a microRNA often overexpressed in cancers, indicating a protective role for LAMP2 in drug resistance of lung cancers." (PMID 35806209, 2022). "LAMP2 could serve as a new marker for the target therapy of lung cancer." (PMID 37986192, 2023).
vacuolar myopathy (6 papers, 2013 to 2025). "A loss-of-function mutation in LAMP-2 gene disrupts autophagy by impairing the fusion between vacuoles and lysosomes, ultimately leading to vacuolar myopathy." (PMID 40308332, 2025). "Recently, it has been shown that differentiating vacuolar myopathy due to LAMP2 variants from other types of vacuolar myopathy can be facilitated by application of p62, microtubule-associated protein 1A/1B-light chain 3 (LC-3), and LAMP2 staining." (PMID 32316520, 2020). "Cytoplasmic increase of LAMP2 has been reported in atrophic fibres in other rimmed vacuolar myopathies." (PMID 24618559, 2014).
ANCA-associated vasculitis (5 papers, 2015 to 2026). "Nevertheless, other research demonstrated that the levels of serum anti-LAMP-2 antibody were similar in ANCA-associated vasculitis (AAV) patients compared to healthy controls (HC)." (PMID 35356030, 2022). "More interestingly, the levels of serum anti-LAMP-2 antibody were remarkably increased in polyarteritis nodosa (PAN) patients compared with ANCA-associated vasculitis and Takayasu arteritis patients (all P < 0.05)." (PMID 35356030, 2022). "A custom ELISA was designed to determine if LAMP-2-ANCA are present in sera obtained from children with systemic vasculitis affecting small-to-medium sized vessels, the most common of which is ANCA-associated vasculitis (AAV)." (PMID 33613565, 2020). "LAMP-2 and anti-LAMP-2 antibodies show the greatest promise for diagnostic use, as proposed concentrations may distinguish PAN from ANCA-associated vasculitis, though methodological variability limits their application." (PMID 41596381, 2026).
Arrhythmia (5 papers, 2021 to 2025). Any cardiac rhythm other than the normal sinus rhythm. "The current study not only improves our understanding of the pathologic mechanisms of how LAMP2 deficiency contributes to cardiac phenotypes but also provides novel therapeutic targets to prevent arrythmia in DD patients." (PMID 36671453, 2022). "To date, an increasing number of LAMP2 mutations have been reported, yet the molecular mechanism of cardiac dysfunction and arrhythmia in DD patients remains unclear." (PMID 36671453, 2022). "To understand the molecular basis of MM treatment related arrythmia in LAMP2 KO CMs, we first compared the mRNA expression of cardiac function related genes in Ctrl and LAMP2 KO CMs by real-time PCR." (PMID 36671453, 2022). "Indeed, our results have identified the over-activation of CaMKII in MM treated LAMP2 KO DD models, confirming the potential role of CaMKII oxidation and activation during the pathogenesis of arrhythmia in DD patients." (PMID 36671453, 2022).
cardiac hypertrophy (5 papers, 2013 to 2023). "Mutations in genes encoding the γ2 subunit of AMP-activated protein kinase (PRKAG2), α-galactosidase A (GLA), and lysosome-associated membrane protein-2 (LAMP2) can cause profound myocardial hypertrophy in association with electrophysiologic defects." (PMID 23700405, 2013). "Also, loss-of-function mutations in LAMP2 leads to profound cardiac hypertrophy and heart failure in patients." (PMID 37596294, 2023).